BRCA1 (BRCA1 DNA repair associated)
Diseases named in the same sentence as BRCA1 in open-access papers (continued):
Sharing a sentence is not in itself a finding about the gene and the disease.
cancer (4,459 papers, 1999 to 2026). A tumor composed of atypical neoplastic, often pleomorphic cells that invade other tissues. "We assessed this in detail for 59 families who had a secondary finding of BRCA1- or BRCA2-related cancer predisposition." (PMID 41950923, 2026). "Owing to a family history of cancer, genetic testing was performed, revealing a pathogenic germline BRCA1 mutation." (PMID 42100405, 2026). "In HR‐deficient tumours exemplified by BRCA1/2‐mutant cancers, PARPis block SSB repair and promote replication‐fork collapse, thereby inducing canonical SL." (PMID 41537447, 2026). "In this review, we summarize the structural and functional domains of BRCA1/2, their pathogenic mutation profiles, and therapeutic strategies targeting BRCA1/2-deficient cancers." (PMID 42274517, 2026). "Treatment of cancers with specific DNA repair defects, including those harbouring BRCA1 or BRCA2 mutations." (PMID 41537447, 2026). "The landscape of hereditary cancer predisposition in senologic and gynecologic oncology extends far beyond BRCA1/2-associated HBOC." (PMID 41528496, 2026). "BRCA1 mutation carriers typically develop cancer in their 30s–40s, while BRCA2 carriers peak later, in their 40s–50s." (PMID 41510186, 2026). "Chemical inhibition of RPA exacerbates genome instability in BRCA1-deficient cancer models treated with PARP inhibitors, leading to loss of ssDNA gap protection, chromosome shattering, and ultimately, cell death." (PMID 42049240, 2026). "The advent of PARPis marks a major milestone in translating SSB repair‐based SL into clinical practice, particularly for cancers harbouring BRCA1/2 mutations." (PMID 41537447, 2026). "The use of PARP inhibitors (PARPi) has profoundly changed the treatment of BRCA1/BRCA2-mutated cancers." (PMID 42244520, 2026). "Results of this screen resulted in seven distinct chemicalscaffolds with EXO1-selective inhibitory activity that synergizedwith the BRCA1-deficiency in human cancer cells." (PMID 40378357, 2025). "Recent research has identified human TATDN2 as a structure-specific RNase that participates in DNA repair under replication stress by resolving R-loops in BRCA1-deficient cancer cells." (PMID 41404808, 2025). "A somewhat newer entity is BRIP1, which exerts its function on a cellular level in conjunction with BRCA1 and has likewise been identified as a cancer susceptibility gene." (PMID 40988318, 2025). "PARP inhibitors (PARPi) have significantly advanced the treatment of cancers harboring BRCA1 or BRCA2 mutations by exploiting deficiencies in homologous recombination-mediated DNA repair." (PMID 41347092, 2025). "A comparison of regional and nationwide cancer cohorts revealed that BRCA1/2 pathogenic variants tended to exceed the expected number between the cohorts, indicating a regional difference." (PMID 40249378, 2025). "In cancers where HR repair is impaired, such as those harboring mutations in BRCA1 and BRCA2 genes, cancer cells heavily rely on alternative DNA repair mechanisms, such as base excision repair (BER), to counteract DNA damage." (PMID 40574045, 2025). "This study aimed to translate, culturally adapt and pilot-test a German version of the 8-item Cancer Worry Scale in individuals carrying BRCA1 or BRCA2 pathogenic variants in Austria." (PMID 40390061, 2025). "The larger correction for BRCA1 PV carriers is consistent with the higher cancer risk and more frequent and earlier uptake of RRSO." (PMID 40399999, 2025). "In 2023, Nanjing Damei Biopharmaceutical developed ATR inhibitors particularly effective against cancers with impaired DNA repair mechanisms, including those with BRCA1/2 mutations, PTEN loss, or ATM deficiency." (PMID 40256842, 2025). "Signature 3, for example, found in 14.4% of pan-cancer samples, is mainly associated with BRCA1/2 pathogenic variants and pathogenic variants in other HRR-related genes, making it a potential biomarker for HRD." (PMID 40069561, 2025).
cancer (continued). "The discovery of pathogenic variants (PVs) in the Breast Cancer Gene 1 (BRCA1) and Breast Cancer Gene 2 (BRCA2) genes, which account for approximately 10–15% of non-mucinous epithelial ovarian cancers (EOC), has revolutionised the management of this disease." (PMID 40805236, 2025). "One major challenge is acquired resistance, where cancer cells restore homologous recombination repair through BRCA1/2 reversion mutations, loss of 53BP1, or increased drug efflux, reducing olaparib’s effectiveness." (PMID 40723906, 2025). "We aimed to investigate the impact of rare germline variants in promoter regions of BRCA1/2 and other 26 cancer predisposition genes on TNBC." (PMID 40338220, 2025). "Having observed killing of engineered BRCA2-deficient cells, we next investigated the sensitivity of cancer cell lines with mutations in BRCA1." (PMID 41359388, 2025). "The GIS is a continuous variable ranging from 0 to >100, whereas HRD is a qualitative parameter that has been defined as GIS ≥42 according to the distribution of GIS in cancer samples harboring a deleterious or suspected deleterious BRCA1/2 mutation." (PMID 40278800, 2025). "It is necessary therefore to evaluate empirically the underlying distribution of the relevant cancer risk factors for BRCA1 and BRCA2 PV carriers." (PMID 40399999, 2025). "Additional studies are necessary before personal cancer risk prediction can include specific type and/or location of the BRCA1 mutation." (PMID 41440233, 2025). "BRCA1 germline variants not only alter the risk of developing certain types of cancer, but also affect the course of cancer treatment." (PMID 40519304, 2025). "There are numerous studies investigating the impact of reproduction and environmental factors on the cancer penetrance among BRCA1/2 mutation carriers." (PMID 40296163, 2025). "To study the cancer development in ER/PR/HER2-negative cells carrying a BRCA1 germline mutation, we established a protocol for the generation of human BRCA1 organoids from ER/PR/HER2-negative heterozygous BRCA1 cells." (PMID 41283387, 2025). "Olaparib is a PARPi showing encouraging success in the treatment of BRCA1-deficient cancers in clinic." (PMID 41243969, 2025). "This potent therapeutic effect underscores the potential of V66-exatecan to exploit the vulnerabilities inherent in BRCA1/2-deficient tumors, offering a promising strategy for treating cancers driven by these mutations." (PMID 41077566, 2025). "This phase Ib trial investigates the side effects of INO-5401 with or without INO-9012 and evaluates a new method of administering vaccines (electroporation) in adult cancer and non-cancer patients with BRCA1 or BRCA2 mutations." (PMID 40243654, 2025). "In this case, the use of platinum-based chemotherapy, which is often effective in BRCA1-associated cancers due to their defects in DNA repair mechanisms, was appropriate." (PMID 40949480, 2025). "The collection of a critical number of healthy persons with BRCA1 mutations is complicated, especially given that “true” cancer-free status can be assigned only after achieving a certain age threshold." (PMID 41374957, 2025). "U. dioica significantly suppressed the expression of Brca1, Brca2, Fas, Lpl, Dgat1 and Mcp1 genes, resulting in significant changes in lipid metabolism, cancer susceptibility and inflammation." (PMID 40153121, 2025). "BRCA1 (breast cancer-associated protein 1) is a critical tumour suppressor strongly linked to the development of several cancers, particularly hereditary breast and ovarian cancer." (PMID 40966517, 2025). "Using a human induced pluripotent stem cell (hiPSC) based model, we characterized an hiPSC line from an invasive cancer patient harboring a BRCA1 mutation." (PMID 40371388, 2025).
cancer (continued). "In our study, multiple MINAS patients developed cancer before the age of 50, and some exhibited tumor types associated with both mutated genes—such as the combination of BRCA1 and MUTYH, suggesting additive or synergistic effects." (PMID 41487526, 2025). "Human TATDN2 functions as a structure-specific RNase to resolve R-loops and is required for the response to replication stress in BRCA1-deficient cancer cells." (PMID 41404808, 2025). "For example, the identification of genetic mutations, such as those in the EGFR gene for lung cancer or BRCA1/2 for breast cancer, can provide early signals of cancer risk or the presence of cancer at a molecular level, often before physical symptoms appear." (PMID 40277534, 2025). "The targeted NGS of 160,790 specimens from multiple cancers, including PCa, revealed that beyond BRCA1/2 genes, a strong association of the genome-wide loss of heterozygosity and biallelic mutations with PCa was found for BARD1, PALB2, and RAD51 paralogs." (PMID 40002276, 2025). "Here, in a prospective cohort of unaffected women with a BRCA1 PV, under imaging surveillance, we seek to determine the impact of PV position and function on cancer risk." (PMID 41440233, 2025). "Both BO and BRCA1/2 mutation diagnoses are diagnosed with the aim of facilitating cancer early detection and improving survival rates." (PMID 39812114, 2025). "An analysis of pan-cancer cohorts recently showed data in other tumors where BRCA1/2 mutation is frequent." (PMID 41020824, 2025). "Thanks to this effect, PARPis quickly became a novel class of anti-cancer drugs, first demonstrating efficiency in treating HR-deficient tumors with a BRCA1 and BRCA2 mutation." (PMID 40616061, 2025). "We are initiating a feasibility study that employs a germline cancer genomic panel of 30–80 high-risk cancer genes, such as BRCA1 and BRCA2, to identify individuals with pathogenic variants." (PMID 40552262, 2025). "PARP inhibitors, which prevent cancer cells from repairing DNA breaks, have been shown to be effective in cancers with DNA repair deficiencies (such as cancers with BRCA1/2 mutations)." (PMID 41194225, 2025). "We successfully identify cancer-associated genes such as BRCA1, BRCA2, PALB2, and TCEAL4, all exhibiting the sought-after expression patterns." (PMID 40983914, 2025). "Considerate portions of patients with BRCA1/2 mutations across various cancers can be potential candidates for PARP inhibitor therapy." (PMID 40274769, 2025). "Pathogenic variants of BRCA1/2 were highly abundant in cancer cohorts compared to the healthy cohort." (PMID 40249378, 2025). "There has been much interest in estimating cancer penetrance according to the specific type and location of a mutation within the BRCA1." (PMID 41440233, 2025). "To do so, we interrogated public datasets to analyze genes upregulated or downregulated when these mutations were present, compared to those with wild-type BRCA1/2 cancers." (PMID 40647506, 2025). "The accumulation of these DNA DSBs results in cell death specifically in DNA DSB repair-deficient cancer cells carrying BRCA1 or BRCA2 mutations through synthetic lethality." (PMID 40308947, 2025). "Homologous recombination deficiency (HRD) causes genomic instability in cancer and is associated with a higher risk of cancer in BRCA1/2 mutation carriers." (PMID 41294748, 2025). "First, we separately analyzed 17 cancer types that included at least three tumors with biallelic deleterious BRCA1/2 mutations or BRCA1 hypermethylation." (PMID 40730886, 2025).
cancer (continued). "This has been exemplified clinically with poly ADP-ribose polymerase inhibitors (PARPi) used to treat cancers with mutations in genes required for homologous recombination – most notably BRCA1 and BRCA2." (PMID 40982437, 2025). "Many of them have been recommended for inclusion in “polygenic risk scores” to assist in the estimation of individual cancer susceptibility for BRCA1/2-carriers." (PMID 41374957, 2025). "In BRCA1 mutation carriers, impaired estrogen signaling causes increased risk for cancer development, metabolic diseases, and sex hormone imbalance with infertility." (PMID 41514592, 2025). "Meanwhile, human TATDN2 possesses RNA 3′ exonuclease and endonuclease activity to resolve R-loops and participates in response to replication stress in BRCA1-deficient cancer cells." (PMID 41404808, 2025). "PARP inhibitors have emerged as a major field of cancer therapy because of their function in DNA repair, especially for tumors containing BRCA1 and BRCA2 mutations." (PMID 40141415, 2025). "On the other hand, recent research showed that TATDN2 is essential for the survival of BRCA1-deficient cancer cells but less so for BRCA1-repleted cancer cells." (PMID 41404808, 2025). "Reversion mutations are a common mechanism of PARPi resistance clinically in BRCA-deficient cancers, particularly small intragenic deletions that restore the reading frame in BRCA1/2." (PMID 41357766, 2025). "Exclusion criteria were BRCA1 gene mutation, women with diagnosed cancer, and women with occupational exposures to Pb." (PMID 40722662, 2025). "As expected, in BRCA-associated cancers, patients with BRCA1/2 biallelic alterations had significantly higher HRD scores than those with monoallelic alterations (P<0.01) and HRR wild-type patients (P<0.001)." (PMID 40420266, 2025). "Synthetic lethality exploitation: Preclinical in vivo models of BRCA1/2-deficient cancers are essential to validate APE1/APE2 inhibition as a therapeutic window, define biomarkers of sensitivity, and identify resistance mechanisms." (PMID 41446759, 2025). "By analogy, BRCAness cancers, i.e., those that share molecular features of germline BRCA1 or BRCA2 mutated cancers (gBRCAm), also phenocopy the platinum-salt or poly(adenosine diphosphate–ribose) polymerase (PARP) inhibitor sensitivity seen in gBRCAm cancers." (PMID 40138429, 2025). "Cancer development in carriers with a BRCA1 variant is a multi-step process that is triggered by several factors and defects, which are not clearly understood." (PMID 41283387, 2025). "Identification of the BRCA1 mutation allowed the healthcare team to adopt a more aggressive and proactive approach to monitoring for other potential cancers." (PMID 40949480, 2025). "PARP1 inhibitors are particularly effective in cancer cells that have DNA repair deficiencies, especially cells with BRCA1/2 mutations." (PMID 40446667, 2025). "Currently available HRD assays typically focus on inactivating genomic alterations in HRR genes (e.g., BRCA1/2) or measure scar-based mutational signatures resulting from HRD only in limited cancer indications." (PMID 41248118, 2025). "Most tumors of BRCA1 germ-line mutation carriers, especially those identified before the age of 50, share morphological characteristics with basal-like cancers and exhibit a basal-like phenotype as determined by immunohistochemistry or expression arrays." (PMID 40141415, 2025). "For instance, mice heterozygous for pathogenic Brca1 mutations are not prone to spontaneous tumors, contrasting with humans who show BRCA1 second hits and cancer predisposition." (PMID 39747084, 2025). "Loss of end protection factors, 53BP1 and REV7, and members of the Shieldin complex have been shown to lead to PARPi resistance in BRCA1-mutated cancers via restoration of HDR." (PMID 41357766, 2025). "BRCA1 (Breast Cancer Susceptibility Gene 1) is a tumor suppressor involved in cell cycle control, DNA repair, checkpoint activation, transcriptional regulation, and apoptosis." (PMID 40732337, 2025).
cancer (continued). "While functional HR allows normal cells to repair DSBs, HR-deficient cancer cells (eg, with BRCA1/2 mutations) cannot, resulting in genomic instability, cell cycle arrest, and apoptotic death." (PMID 41236806, 2025). "Against CST, cisplatin selectivity was 113.6-fold compared to MSCL-1, which accounted for the loss of BRCA1 function of this cancer line, making it hypersensitive to DNA-damaging agents." (PMID 41373545, 2025). "The groundbreaking aspect of using olaparib in human medicine for treating cancers with BRCA1 and BRCA2 mutations was demonstrated in patients with metastatic breast tumors that harbor BRCA1/2 mutations, achieving an overall response rate (OR) of 50%." (PMID 40004231, 2025). "Clinically, PARP inhibitors exploit the HR defect in BRCA1-deficient cancers and are a highly effective systemic treatment with limited toxicity." (PMID 41243969, 2025). "TATDN2 has recently been implicated in resolving R-loops and participating in the replication stress response in BRCA1-deficient cancer cells." (PMID 41404808, 2025). "Despite the initial durable response of PARP inhibitors in BRCA1/2-mutated cancers, most patients develop PARP inhibitor resistance." (PMID 40274769, 2025). "The dysregulation of these ncRNAs has been implicated in key cancer characteristics such as invasion, proliferation, and treatment resistance, particularly in the context of BRCA1 mutations." (PMID 39997609, 2025). "In BRCA1-mutated cancers, loss of these end protection factors restores HDR by allowing for resection of the damaged DNA ends to enable HDR." (PMID 41357766, 2025). "BRCA1 is essential for HR, and since HR deficiency promotes the toxicity of PARPi, the effect of PARPi is maximized in BRCA1-mutated, HR-deficient cancers." (PMID 39844055, 2025). "Mutations in BRCA1/2 genes, especially in cancers such as ovarian, breast, and endometrial cancer, result in increased cellular sensitivity to PARP inhibitors." (PMID 40647471, 2025). "The ePOWER (empowering Preventive Options for Women Experiencing Risk) intervention is designed to help BRCA1/2 previvors manage their cancer-related uncertainty and make informed health decisions." (PMID 40485758, 2025). "In the studies that focused on additional cancers associated with BRCA1 mutations, increased risk has been reported." (PMID 40406258, 2025). "Conversely, 0.4% of patients, as revealed by our study, harbor such variants in BRCA1 or MET genes associated with dominant cancer risk." (PMID 39344744, 2025). "Numerous authors have demonstrated that polymorphisms in genes encoding DNA glycosylases, such as UNG and POLG, can modify the risk of cancer development in carriers of BRCA1 and BRCA2 mutations, a high-risk group." (PMID 40647471, 2025). "This is the first study analyzing the immediate outcomes of NACT in BRCA1- vs. BRCA2-associated cancers." (PMID 40547808, 2025). "The remaining eight participants had P/LP BRCA1/2 variants confirmed and were referred to the cancer genetics and high-risk surveillance program." (PMID 41463058, 2025). "Women with confirmed BC‐linked genetic variants, such as BRCA1/2 mutations, require accurate cancer risk estimation and appropriate guidance for risk reduction." (PMID 40523654, 2025). "Pathogenic BRCA1 germline variants can dramatically increase the risk of cancer development in affected individuals." (PMID 40519304, 2025). "Olaparib, a PARP inhibitor, has received FDA approval for the treatment and maintenance of several cancers, particularly those with a germline BRCA1 or BRCA2 mutation, including HER2-negative metastatic breast cancer." (PMID 40723906, 2025). "Most individuals carrying cancer susceptibility gene variants, such as BRCA1, BRCA2, and ATM, are heterozygous for a single pathogenic variant." (PMID 40777133, 2025).